SCAT1 (S-phase cancer associated transcript 1)
Synonyms: CTD-2357A8.3; XLOC_012582; LINC02081
Gene: Long non-coding RNA gene on chromosome 17 (78,605,233 to 78,632,155, reverse strand). Ensembl gene ENSG00000267123.
Diseases named in the same sentence as SCAT1 in open-access papers:
SCAT1 is named in the same sentence as 7 diseases in open-access papers, as found by Europe PMC text mining. Sharing a sentence is not in itself a finding about the gene and the disease. The quoted sentences say what the papers report.
esophageal squamous cell carcinoma (2 papers, 2021 to 2022). Esophageal squamous cell carcinoma (ESCC) is a type of esophageal carcinoma (EC) that can affect any part of the esophagus, but is usually located in the upper or middle third. "It’s reported that SCAT1 as a component of the three-lncRNA signature predicting pathological response and outcome in esophageal squamous cell carcinoma with neoadjuvant chemoradiotherapy shows a compellent prognostic value in patients." (PMID 36419649, 2022).
lung cancer (2 papers, 2020 to 2021). A malignant neoplasm involving the lung. "SCAT1 was reported upregulated in 10 different cancer types and identified a functional involvement as well as independent prognostic capacity in several cancers, including non‐small cell lung cancer." (PMID 32898328, 2020).
cancer (6 papers, 2018 to 2024). A tumor composed of atypical neoplastic, often pleomorphic cells that invade other tissues. "Besides, although alternative splicing of SCAT1 has yet been reported, its expression type has been found to be associated with cancer prognosis and immunotherapy response." (PMID 38735973, 2024). "Some of the irlncRNAs previously associated with the malignant phenotypes of various cancers, including MIAT, TYMSOS, LINC01063, HOXC-AS1, LINC02454, SCAT1, and LINC01322 were identified in the process of modeling in this study." (PMID 34167440, 2021). "SCAT1 is differentially expressed in 10 cancers, including LUAD and LUSC." (PMID 29491376, 2018). "Thus, our functional and clinical investigations on SCAT8, SCAT5, and SCAT1, suggests that our cell cycle-based functional screen indeed has identified potential lncRNA-based cancer drivers." (PMID 29491376, 2018). "Similarly, SCAT1, which is upregulated in 10 different cancers, shows a functional involvement and independent prognostic capacity in four cancers including LUAD and LUSC." (PMID 29491376, 2018). "Our clinical investigations revealed CTD-2357A8.3 (SCAT1) and LUCAT1 (SCAT5) as common independent prognostic biomarkers for lung and kidney-derived cancers, respectively." (PMID 29491376, 2018). "With the exception of the lncRNAs SCAT1, LINC00320, PURPL, and TP53TG1, associated with the risk of certain types of cancer or genetic diseases, no other associations with human disorders were found." (PMID 36768581, 2023).
tumor (2 papers, 2020 to 2021). "Almost all the genes in the ceRNA network have reported that they enrolled or associated with tumor progression, except for LINC02473, LINC0170, VPS9D1-AS1, C11orf44, and SCAT1." (PMID 32426332, 2020). "Importantly, we validated these biomarkers using qRT-PCR and found that the gene expression rate of protective factors such as AC093159.1/ TYMSOS, SCAT1 /LINC00460 and Z82243.1/LINC02561 was significantly higher in early versus late tumor stages." (PMID 34167440, 2021).
SCAT1 also shares sentences with these, for which no sentence is quoted: cyst (1 paper); esophageal cancer (1); genetic diseases (1).